IL1R2 (interleukin 1 receptor type 2)
Diseases named in the same sentence as IL1R2 in open-access papers (continued):
Sharing a sentence is not in itself a finding about the gene and the disease.
inner ear disease (1 paper, 2009). "The induction of IL1R2 by IL-4 certainly suggests that the maintenance of a TH2-like phenotype is important in controlling inner ear disease, whereas expression of IFNγ, that fosters a TH1-like response, has been observed in AIED patients, and blocks the expression of IL1R2." (PMID 19401759, 2009).
leukemia (1 paper, 2023). A malignant (clonal) hematologic disorder, involving hematopoietic stem cells and characterized by the presence of primitive or atypical myeloid or lymphoid cells in the bone marrow and the blood. "LSP1 was highly expressed in most leukemia cell lines (shown in the dotted box), while IL1R2, MPO, and CRIP1 were highly expressed in one or two leukemia cell lines." (PMID 37691822, 2023).
meningitis (1 paper, 2021). A disorder characterized by acute inflammation of the meninges of the brain and/or spinal cord. "Interestingly, anti-inflammatory cytokines detected in the CSF of meningitis patients such as IL10, TGFβ or the IL1 receptor antagonists IL1Rs and IL1R2 could not be detected in this study, suggesting that the CP epithelium might not be the source of these factors during meningitis." (PMID 34863201, 2021).
renal cell carcinoma (1 paper, 2023). "In renal cell carcinoma, IL1R2 promotes tumor progression through the JAK2/STAT3 pathway." (PMID 37728418, 2023).
sarcoidosis (1 paper, 2013). Sarcoidosis is a multisystemic disorder of unknown cause characterized by the formation of immune granulomas in involved organs. "The top 50 overexpressed inflammatory genes in the ‘good treatment response’ sarcoidosis patients included anti-inflammatory genes e.g IL1R2, DUSP1, IL18R, C-FOS, IκBα and MAPK1." (PMID 23940611, 2013).
sarcoma (1 paper, 2019). A usually aggressive malignant neoplasm of the soft tissue or bone. "Different from other cancer subtypes, the overexpression of our identified peptide-derived protein interleukin-1 receptor type 2 promotes the initiation and progression of sarcoma." (PMID 31850330, 2019). "The first rule of our identified quantitative rule based on dataset-2 involves a unique peptide, HQKNDSANTVITTWLTRGSC, which can be further realigned to the protein interleukin-1 receptor type 2 with acceptable mismatches that contribute to the identification of sarcoma." (PMID 31850330, 2019).
staphylococcus aureus infection (1 paper, 2021). An infectious process in which the bacteria Staphylococcus aureus is present. "Elevation of IL1R2 expression and soluble IL1R2 concentrations are correlated with severity of Escherichia coli and Staphylococcus aureus infections." (PMID 33256556, 2021).
stomach carcinoma (1 paper, 2022). "Further bioinformatics analysis of the ASCL2 in STAD patients using the cBioPortal and GEPIA system shows that the ASCL2 may be related to CNTNAP3, CLIP1, C9orf84, ARIH2, and IL1R2 mutations and involved in stomach carcinoma prognosis, which requires further verification in future studies." (PMID 36008864, 2022).
thyroid cancer (1 paper, 2023). "They found that rs3917225 in IL1R1 as well as rs2072472 and rs11674595 in IL1R2 were linked to susceptibility to thyroid cancer." (PMID 37189693, 2023).
triple-negative breast carcinoma (1 paper, 2025). An invasive breast carcinoma which is negative for expression of estrogen receptor (ER), progesterone receptor (PR), and human epidermal growth factor receptor 2 (HER2). "Additionally, the combination of IL-1R2 neutralizing antibodies with anti-PD-1 therapy has demonstrated potent antitumor efficacy in triple-negative breast cancer (TNBC) patients." (PMID 40767963, 2025).
vaginal disorder (1 paper, 2019). A non-neoplastic or neoplastic disorder that affects the vagina. "IL1R2 polymorphisms have been considered as genetic factors associated with cervical cytokine concentrations in African American and European American women, and the changed cytokine level was related to vaginal disorder." (PMID 30460760, 2019).
Venous thrombosis (1 paper, 2019). Formation of a blood clot (thrombus) inside a vein, causing the obstruction of blood flow. "Some studies reported that IL1R1 and IL1R2 SNPs are associated with venous thrombosis and immune and inflammatory disease." (PMID 30672138, 2019).
tumor (66 papers, 2008 to 2025). "In tumor cells, we found that IL-1R2 deficiency led to decreased tumorigenesis and increased immunogenic programs." (PMID 40767963, 2025). "For instance, a study in triple-negative breast cancer (TNBC) identified IL1R2 expression in a specific subset of tumor-associated macrophages (TAMs), where it acts as a master regulator of immunosuppression." (PMID 41415279, 2025). "Genes associated with cell migration and proliferation, such as Klf12, Rhoj, and Vctn1, were down-regulated in IL-1R2 deficient tumor cells." (PMID 40767963, 2025). "Our findings revealed that IL-1R2 deficient mice exhibited a significant reduction in tumor burden, accompanied by alterations in the carcinogenic program and enhanced immunogenicity of tumor cells." (PMID 40767963, 2025). "IL1R2, a decoy receptor that inhibits IL-1 signaling, has been implicated in immune suppression within the tumor microenvironment." (PMID 40227838, 2025). "Unsupervised clustering of RNASeq data revealed two distinct transcriptional groups, that shared strong expression of CD70 and IL1R2, previously linked to tolerogenic tumor microenvironments." (PMID 37495858, 2023). "Whole-genome expression analysis revealed a strong correlation between acquired resistance and stem cell characteristics and increased expression of IL1R2, an immunosuppressive regulator overexpressed in various tumour entities and linked to poor prognosis." (PMID 37460712, 2023). "RNAseq data for myeloid cell types collected at the onset of CRS revealed that IL-1R1 was up-regulated in tumor-associated myeloid cells, while only IL-1R2 was detected in spleen myeloid cells." (PMID 36100873, 2022). "This inflammatory condition was associated with increased recruitment of non-antigen specific Tregs, which displayed two major functional states characterized by high expression of Il1r2 or Klrg1, and associated with a tumor-infiltrating and a tissue-resident signature, respectively." (PMID 35211118, 2022). "In the future, it will be necessary to combine other models to more accurately investigate the role of IL-1R2 in the tumor microenvironment." (PMID 40767963, 2025). "We analyzed the expression of IL-1 signal-related genes in epithelial cells, and the results showed that the expression of Il1r1 was decreased in tumor cells after the deletion of IL-1R2, suggesting a decreased IL-1 signaling in Il1r2−/− tumor cells." (PMID 40767963, 2025). "Tregs sequester available IL-1β in the tumor microenvironment (TME), a mechanism that positions IL-1R2 as an active orchestrator of tumor immune escape." (PMID 41415279, 2025). "The upregulation of IL1R2 has been shown to orchestrate an immunosuppressive tumor microenvironment, promote tumor proliferation and invasion, and activate the expression of angiogenic factors." (PMID 40517318, 2025). "Collectively, these findings underscore the multifaceted role of IL-1R2 in regulating tumor progression and antitumor immune responses, highlighting its potential as a therapeutic target in CRC." (PMID 40767963, 2025). "In breast cancer, IL1R2 has been identified as a promoter of TICs self-renewal and tumor progression, especially in TNBC." (PMID 41373619, 2025). "Among these 23 TLSRGs, CCL19, CCL21 and IL1R2 were highly expressed in normal tissues, while the rest genes were highly expressed in tumor tissues." (PMID 39493749, 2024). "In CRC, apCAFs are significantly positively correlated with Tregs, similar to findings where IL1R2 expressed by Tregs in a mouse MC38 cell tumor model enhances the interaction between Tregs and CAFs by upregulating MHC class II molecules on CAFs." (PMID 38903527, 2024). "IL1R2 constitutes a decoy interleukin receptor, that abrogates interleukin-1 signaling and is known for strong expression in serum and tumor tissue in EBV-related Hodgkin lymphoma." (PMID 37495858, 2023).
tumor (continued). "Supporting this, specific blockade of IL-1R2 in Tregs in their murine models improved anti-tumour immunity upon ICI therapy in several murine models." (PMID 36480035, 2023). "The authors show that IL-1R2, a decoy receptor for IL-1β, is exclusively expressed by tumour-infiltrating Tregs in several murine and human cancer types." (PMID 36480035, 2023). "Collectively, these results suggest that IL-1R2 is induced in cancer cells, often correlating with bad prognosis, and in tumor infiltrating leukocytes." (PMID 35211118, 2022). "Multiple immune–epithelial interactions involving T/NK cells and McDCs with tumor epithelial cells were predicted in i3 cancers (for example, IL1B in McDCs to IL1R2 in i3 tumor cells)." (PMID 35773407, 2022). "Conversely, other immunoregulatory genes, such as CD274 (coding for PD-L1), IL1R2 (decoy IL1 receptor), and CD163 (marker of M2 and tumor-associated macrophages) were found to be upregulated at the time of diagnosis." (PMID 36230815, 2022). "As cytokines have paracrine action and play an important role in the tumor microenvironment, the cytokine-cytokine receptor pathway was analyzed and found that many anti-inflammatory factors (IL1R2, IL1B, and IL20) were decreased." (PMID 34122668, 2021). "It has been reported that IL1R2 expressed on activated tumor Tregs and is correlated with poor prognosis in lung adenocarcinoma." (PMID 33293583, 2020). "It has been reported that Ikzf4 and Il1r2 are preferentially expressed in Treg cells, especially tumor-infiltrating Treg cells." (PMID 33644036, 2020). "In vivo xenograft results demonstrated that IL1R2 overexpression facilitated xenograft tumor growth and increased BTICs in immunodeficient female mice." (PMID 31921558, 2020). "As a decoy receptor, IL‐1R2 is a natural inhibitor of IL1 and plays important roles in tumor‐associated inflammation and immune regulation." (PMID 30895747, 2019). "IL-1 family members, IL-1R2 and IL-18R and IL-36γ, were all significantly induced in tumor-bearing p204 KO mice, suggesting that p204 is also an important regulator of inflammation." (PMID 29691417, 2018). "Expression of IL-1R1, however, has to be viewed in the context of IL-1R2 expression, which, according to our in situ hybridization patterns, was present in stronger signal intensities and in larger proportions of tumor cells than expression of IL-1R1." (PMID 26406983, 2015). "Hodgkin and Reed-Sternberg (HRS) cells of all cases expressed low IL-1R1 transcript levels in some tumor cells, and high levels of IL-1R2 in large proportions of HRS cells." (PMID 26406983, 2015). "Targeting IL1R2 is considered effective for inhibiting tumor angiogenesis as IL-1 is essential in tumor angiogenesis and invasiveness." (PMID 24670367, 2014). "Histopathological analysis showed that the tumor malignancy of Il1r2−/− mice after treatment was significantly reduced compared with the control group, which further indicated that IL-1R2 blocking combined with immune checkpoint inhibitor therapy can effectively slow tumor growth." (PMID 40767963, 2025). "However, studies have explored the feasibility of using neutralizing antibodies and RNA interference technology to inhibit IL-1R2 in tumor models." (PMID 40767963, 2025). "Furthermore, immunohistochemical analysis revealed higher IL1R2 expression in tumor tissues of LUAD patients, with lower IL1R2 levels being associated with better prognosis." (PMID 41417784, 2025). "The reduction of tumor burden is more significant when combining IL-1R2 deletion and ICIs." (PMID 40767963, 2025). "Our data suggest that blockade of IL-1R2 reduces inflammation and tumor progression." (PMID 40767963, 2025). "In fact, single-cell sequencing results showed that fewer tumor cells were observed in Il1r2−/− mice, suggesting that IL-1R2 deletion may lead to reduced tumor epithelial cell proliferation." (PMID 40767963, 2025).
tumor (continued). "However, further investigation is required to validate this mechanism and to elucidate the broader implications of IL-1R2 signaling in the tumor microenvironment." (PMID 40767963, 2025). "In addition, IL1R2 was included in a signature consisting of 9 genes that predicted tumor stages and survival of PDAC patients." (PMID 35211118, 2022). "However, the stimuli that promote IL-1R2 expression in tumor-infiltrating Treg cells and the function of IL-1R2 in this subset are still to be identified." (PMID 35211118, 2022). "Data generated until now show that IL-1R2 is generally up-regulated in tumor tissue." (PMID 35211118, 2022). "Several studies investigated IL-1R2 expression in cancer cells or in the tumor microenvironment, to elucidate whether the IL-1R2 could be involved in tuning IL-1-dependent cancer-related inflammation." (PMID 35211118, 2022). "Whereas, tumor regulatory T cells including IL1R2 are correlated to poorer LUAD prognosis." (PMID 36034461, 2022). "However, further studies are needed to elucidate the functional role of IL-1R2 in tumor-infiltrating Treg cells and other immune cells." (PMID 35211118, 2022). "Interestingly, the decoy receptor IL1R2 was expressed at low levels in fibroblasts, while its expression in tumor cells was variable but high in most of the CCCL tested." (PMID 34066976, 2021). "IL-1R2 up-regulation may be another mechanism through which tumor-residentTreg cells inhibit anti-tumor immune response through neutralizing effector cellIL-1β function." (PMID 33704402, 2021). "Furthermore, knockdown of BMI1 or USP15 inhibited the enhanced tumor growth by IL1R2 overexpression in vivo, and also inhibited the BTICs enrichment in the xenograft tumors." (PMID 31921558, 2020). "Interleukin‐1 receptor type 2 (IL1R2) is a decoy receptor for IL‐1 cytokines and involved in host inflammatory and immune progression which could lead to the lesion and neoplasia of cervix." (PMID 30460760, 2019). "Compared with C-MOs, MAMPCs expressed higher levels of TAM signature genes (i.e., Arg1, Cdh1, Hmox1, Il1r2, Mrc1, and Stab1) that were also highly expressed by MAMs, suggesting that differentiation of C-MOs to MAMPCs (M-MDSCs) is directed toward the tumor-promoting macrophages." (PMID 29387063, 2017). "Data suggest a paracrine function of IL-1beta in HL lesions and a modulatory role of IL-1R2 as a specific product of HRS cells likely to inhibit possible differentiating functions of IL-1 on the tumor cell itself, and to induce anergy in the surrounding lymphoid tissue." (PMID 26406983, 2015). "IL-1R2 thereby may contribute to the spectrum of tumor induced immune escape mechanisms by inhibition of IL-1, one of the earliest general T-cell co-stimulatory molecules and by deprivation of HRS cells from regulation by IL-1." (PMID 26406983, 2015). "Notably, the deletion of IL-1R2 was associated with increased CD8+ T cell exhaustion and enhanced antigen presentation by dendritic cells, suggesting that IL-1R2 modulates both the immunogenicity of tumor cells and the functionality of key immune populations within the TME." (PMID 40767963, 2025). "Although IL1R2‐neutralizing antibody significantly inhibited cancer cell growth, invasion and chemoresistance in vitro, the application of neutralizing antibody in vivo showed a relatively mild inhibitory effect on tumor growth and chemoresistance to docetaxel in an immunodeficient mouse model." (PMID 31921558, 2020). "Many of these genes, including those encoding bFGF, MAPK10, MAP3K5, IL1R2, E-cadherin, Ki67, Cyclin E1, beta-catenin, 14-3-3 protein T-cell (YWHAQ), integrin alpha-V (ITGAV), integrin alpha-10 (ITGA10), CDK6, PCNA, CDKN1A, and PAK3, are related to tumor metastasis and regulation of cell migration." (PMID 28454092, 2017). "Targeting IL1R2 may be an appropriate therapeutic strategy for inhibiting tumor angiogenesis." (PMID 18211683, 2008).
tumor (continued). "In that study, the most abundant cytokine-receptor pair interaction between TAMs and tumor cells was predicted for IL1B and its decoy receptor IL1R2, suggesting inhibition of IL1B-mediated proinflammatory signaling by tumor cells." (PMID 40666494, 2025). "P.g. induces macrophage polarization into tumor-associated M2, upregulating gene expression of pro-tumoral molecules (suprabasin, IL-1R2, IL-18, and TGF-α) while suppressing multiple anti-tumor cytokines (TNF-β, IFN-β, TRAIL, and TNF-α) in Cal-27 cells." (PMID 40924302, 2025). "Further analysis of the differential expression of IL-1 family and related genes in normal tissues and HPV- and HPV+ tumor tissues revealed that IL-1α, IL-1β, IL1R1, IL1R2, IL1RL1, IL1RAP, IL1F10, IL-18 and CASP1 were highly expressed in HPV- tumors." (PMID 39461030, 2024). "Conversely, a negative correlation was observed between the production of interleukin 1 alpha (IL1A) by CAFs and the expression of its receptors—IL1R1, IL1R2, and IL1RAP—on tumor cells." (PMID 39519201, 2024). "Using this same Treg gating strategy, we next examined the surface expression of eight protein markers (CD30, OX40, 4-1BB, TIGIT, PD-L1, IL-1R2, IL-21R, and CCR8) on tumor-infiltrating Tregs of five CRC patients from our South-East Asian cohort." (PMID 33527196, 2021). "IL1R2 intracellular domain (icd-IL1R2) interacts with USP15, enhancing its deubiquitination and stabilization of a cell cycle regulator and tumor growth promoter, BMI1." (PMID 34575114, 2021). "Tumor-infiltrating Tregs have been shown to exhibit a distinct signature comprising the co-stimulatory molecules (OX40, 4-1BB), cytokine receptors (IL1R2, IL21R, CCR8, CD30), and co-inhibitory molecules (PD-L1, TIGIT)." (PMID 33527196, 2021). "A positive correlation between IL1R2 and BMI1 was also observed in both BC tissues and xenograft tumor tissues." (PMID 31921558, 2020). "From the high levels of IL-1R2 RNA and protein expression by HRS cells one can assume that the surrounding lymphoid tissue, neighboring the tumor cells, is rendered unresponsive by inhibition of IL-1 dependent activation." (PMID 26406983, 2015). "IL-1R2 plays a crucial role in the tumor microenvironment, but there are currently no approved therapeutic agents targeting IL-1R2." (PMID 40767963, 2025). "Furthermore, the deletion of IL-1R2 resulted in an increased proportion of exhausted CD8+ T cells, a population commonly enriched for tumor antigen-specific T cells, suggesting an augmentation of tumor-specific immune responses." (PMID 40767963, 2025). "IL1R2 blockade significantly reduces the BCSCs population, inhibits macrophage recruitment and M2 polarization, and prevents CD8+ T-cell exhaustion, collectively contributing to tumor suppression." (PMID 41373619, 2025). "Although this study provides valuable insights, there are certain limitations: due to the use of IL-1R2 total knockout mice, it was not possible to determine which cell type plays a dominant role in the anti-tumor response." (PMID 40767963, 2025). "In addition to immune checkpoints (PD-L1/L2, LAG3, TIM-3) strongly expressed IL1R2 and CD70 can inhibit immune responses and create a tolerogenic tumor microenvironment (TME)." (PMID 37495858, 2023). "Further heterogeneity has been reported within Tregs present in the tumor, which is characterized by the expression of activation molecules such as TNF receptor superfamily member 9 (TNFRSF9) and Interleukin 1 receptor type 2 (IL1R2)." (PMID 36032082, 2022). "Other tumor-specific Treg signature genes (e.g., CCR8, FCRL3, IL1R2) are exclusively expressed on tumor-infiltrating Tregs and absent in their peripheral counterparts." (PMID 33679808, 2021). "Notably, CRC tumor-infiltrating Tregs can be distinguished by the increased expression of a panel of signature markers, including CD30, IL1R2, IL21R, OX40, CCR8, PD-L1, TIGIT, and 4-1BB." (PMID 33527196, 2021).